PAICS (phosphoribosylaminoimidazole carboxylase and phosphoribosylaminoimidazolesuccinocarboxamide synthase)
Diseases named in the same sentence as PAICS in open-access papers (continued):
Sharing a sentence is not in itself a finding about the gene and the disease.
melanoma (10 papers, 2013 to 2025). A malignant, usually aggressive tumor composed of atypical, neoplastic melanocytes. "We also analyzed the consequences of PAICS deficiency in MelJuSo melanoma cells using a subcutaneous xenograft tumor model." (PMID 23717670, 2013). "Moreover, mutations in PAICS have been reported in human melanoma through whole-exome sequencing and SNP array profiling of six cutaneous melanoma cell lines derived from metastatic patients." (PMID 30097015, 2018). "Immunohistochemical analysis confirmed the overexpression of PAICS in human melanoma samples compared to expression in normal skin biopsies." (PMID 30097015, 2018). "Our observation that PAICS knockdown inhibits cell proliferation concurs with similar observations in melanoma cells." (PMID 26140362, 2015). "PAICS (Phosphoribosylaminoimidazole carboxylase/phosphoribosylaminoimidazole succino-carboxamide synthetase) was identified in the melanoma lung metastasis screen." (PMID 23717670, 2013). "We subsequently confirmed that PAICS protein is overexpressed in melanomas when compared with normal skin using an anti-PAICS antiserum." (PMID 23717670, 2013). "The induced knockdown of PAICS in MelJuSo melanoma cells also decreased tumor xenograft growth; however, the difference compared with tumor growth of the parental cell line with endogenous PAICS expression was rather small." (PMID 23717670, 2013). "MelJuSo and other established melanoma cell lines express prominent amounts of PAICS protein exceeding the PAICS levels observed in the spontaneously immortalized human keratinocyte cell line HaCaT and in human foreskin fibroblast cells." (PMID 23717670, 2013). "Stable knockdown of PAICS increased the sensitivity of melanoma cells to cisplatin and staurosporine treatment." (PMID 23717670, 2013). "MITFA and SOX10 have previously been identified as specific markers of malignant zebrafish melanomas in the original study, while PAICS and COX6A2 are newly discovered by our study, which actually play important biological roles and molecular functions in tumor development." (PMID 39494219, 2024). "Because we isolated PAICS from the melanoma metastasis cDNA library and found PAICS protein levels to be upregulated in melanomas, we targeted PAICS expression in the human melanoma cell line MelJuSo by lentiviral transduction with three different PAICS shRNA sequences cloned into the pGIPZ vector." (PMID 23717670, 2013). "Other examples include HIGD1A and PAICS (both found in the melanoma library)." (PMID 23717670, 2013). "NRAS Q61L melanomas were most enriched for modules 7 (C19orf10, ARF4, KDELR2), 13 (TIMM50, ZBED3-AS1, SERPINF1), and 15 (RAP1GAP, OCA2, PAICS)." (PMID 39796775, 2025). "In addition, it has been demonstrated that c-Myc plays a critical role in the maintenance of expression of PRPS2, PPAT, TrifGART, PAICS and IMPDH2 in melanoma cells and of PPAT, IMPDH1, IMPDH2 but not PAICS in a human lymphoma model cell line." (PMID 38444943, 2024). "Very recently, polyubiquitination of PAICS by the ubiquitin ligase ASB11 was shown to favorize the recruitment of the ubiquitin-binding protein UBAP2 and therefore trigger purinosome formation and enhance DNPNB in melanoma cells." (PMID 38444943, 2024). "MUC19, PAICS, RBMXL1, KIF23 have been identified in melanoma, which might deserve further investigations the role in cancer." (PMID 28159935, 2017). "In both cases, the colony numbers were significantly reduced in the absence of PAICS, thereby confirming that PAICS plays an important role in the tumorigenicity of melanoma cells." (PMID 23717670, 2013). "We also identified mutations in four genes (MUC19, PAICS, RBMXL1, KIF23) never reported in melanoma, which might deserve further investigations." (PMID 23704925, 2013).
melanoma (continued). "IHC analysis revealed significant PAICS protein overexpression in melanoma samples compared with normal skin biopsies; this result was confirmed when the IHC analysis was repeated with a cohort of 39 melanomas in which the PAICS expression levels were compared with 25 normal skin samples." (PMID 23717670, 2013).
bladder cancer (8 papers, 2013 to 2024). "A study of the oncogenic mechanism of PAICS has revealed that PAICS can induce epithelial-mesenchymal transition in bladder cancer by positively regulating SNAI1 and reducing E-cadherin expression." (PMID 32632107, 2020). "Our previous studies have demonstrated a function for PAICS in cancer cell proliferation and the invasion and growth of lung, prostate, and bladder cancers." (PMID 32218208, 2020). "Analysis of the Oncomine database demonstrated that PAICS mRNA is significantly overexpressed in a variety of tumor entities, including colorectal cancer, brain and CNS cancer, bladder cancer and lymphoma." (PMID 23717670, 2013). "Moreover, in bladder cancer, it was demonstrated, as we observed, that miR-128 was one of the regulating miRNAs of PAICS." (PMID 32218208, 2020). "The essential role of PAICS in prostate cancer and bladder cancer was previously demonstrated." (PMID 33281602, 2020).
gastric cancer (8 papers, 2020 to 2024). A primary or metastatic malignant neoplasm involving the stomach. "Meanwhile, loss of PAICS can not only impede the growth of gastric cancer cells but also induces their apoptosis and DNA damage." (PMID 35379785, 2022). "The downregulation of PAICS can enhance the sensitivity of gastric cancer cells to cisplatin and inhibit gastric cancer cell growth." (PMID 38920983, 2024). "have reported that PAICS participates in DNA damage repairing by targeting HDAC1‐DAD51 in gastric cancer." (PMID 38463398, 2024). "In this study, PAICS deficiency induced DNA damage in EGFR wild‐type NSCLC cells, which is consistent with the role of PAICS in gastric cancer." (PMID 38463398, 2024). "Phosphoribosylaminoimidazole carboxylase and phosphoribosylaminoimidazole succinocarboxamide synthetase (PAICS) was upregulated in gastric cancer (GC)." (PMID 36968022, 2023). "However, the specific biological roles and related mechanisms of PAICS in gastric cancer (GC) remain unclear." (PMID 32632107, 2020). "Apart from the metabolic role of PAICS, its knockdown was found to induce DNA damage and to impair DNA damage repair by reducing HDAC1/2 deacetylase activity and to enhance the sensitivity to DNA damaging agents like cisplatin in gastric carcinoma in vitro and in vivo." (PMID 37172090, 2023).
lung adenocarcinoma (8 papers, 2015 to 2024). A carcinoma that arises from the lung and is characterized by the presence of malignant glandular epithelial cells. "Expression of PPAT and PAICS was independently associated with patient survival in lung adenocarcinomas; further, a subset of adenocarcinoma patients harbour aneuploidy and amplification in divergently transcribed loci of PPAT and PAICS." (PMID 34205450, 2021). "Tissue microarray analysis by immunohistochemistry (IHC) using specific antibodies against PPAT and PAICS showed increased staining in lung adenocarcinomas." (PMID 26140362, 2015). "We showed that PPAT and PAICS of de novo purine biosynthesis are up-regulated in lung adenocarcinomas." (PMID 26140362, 2015). "Transcript analyses from next-generation RNA sequencing and gene expression profiling studies suggested that PPAT and PAICS can serve as prognostic biomarkers for aggressive lung adenocarcinoma." (PMID 26140362, 2015). "Varambally‘s laboratory reported that PPAT and another enzyme PAICS in the purine biosynthesis pathway may drive lung adenocarcinoma cells to switch to aerobic glycolysis (the Warburg Effect)." (PMID 33520699, 2020). "Similarly, H23 (lung adenocarcinoma cells) with PAICS knockdown showed reduced cell proliferation and a decrease in CAM tumor growth." (PMID 26140362, 2015). "We discovered increased expression of phosphoribosyl amidotransferase (PPAT) and phosphoribosylaminoimidazole carboxylase, phosphoribosylaminoimidazole succinocarboxamide synthetase (PAICS) enzymes of de novo purine biosynthetic pathway in lung adenocarcinomas." (PMID 26140362, 2015). "Thus amplification could be one of the potential mechanisms of increased expression of PPAT and PAICS in a subset of lung adenocarcinomas." (PMID 26140362, 2015). "In order to identify the possible genomic events for PPAT and PAICS dysregulation, we performed fluorescence in situ hybridization (FISH) with lung adenocarcinoma samples." (PMID 26140362, 2015).
colorectal cancer (7 papers, 2013 to 2024). A primary or metastatic malignant neoplasm that affects the colon or rectum. "Although PAICS has been implicated as a potential therapeutic target in several cancers, its clinical and prognostic significance in colorectal cancer (CRC) is not fully understood." (PMID 33596246, 2021). "We also knocked down GART and PAICS, 2 key enzymes for de novo purine synthesis, in colorectal cancer cells." (PMID 37252797, 2023). "In colorectal cancer cells, knockdown of phosphoribosylaminoimidazole carboxylase, phosphoribosylaminoimidazole succinocarboxamide synthetase (PAICS) induced higher levels of E-cadherin and lower levels of vimentin." (PMID 34439333, 2021). "Clinicopathological characteristics of colorectal cancer patients according to PAICS expression by immunohistochemistry." (PMID 33596246, 2021). "Overall, the findings point to the usefulness of PAICS targeting in the treatment of aggressive colorectal cancer." (PMID 32218208, 2020). "Increased expression of PAICS is involved in the proliferation, migration, invasion, and growth of colorectal cancer (CRC) cells, while depleting PAICS in the mice reduced tumor growth and metastasis to the liver, lung, and bones." (PMID 35096022, 2021).
prostate carcinoma (7 papers, 2020 to 2024). A carcinoma that arises from epithelial cells of the prostate gland. "Furthermore, its high expression has also been associated with the aggressiveness of the prostate cancer; therefore, PAICS has been considered essential for the proliferation and invasion of prostate cancer cells." (PMID 35096022, 2021). "In prostate cancers, the oncogenic protein Myc is involved in the regulation of PAICS expression." (PMID 32218208, 2020). "Our previous study shows that, in prostate cancers, the bromodomain inhibitor JQ1 decreases PAICS expression by interfering with Myc binding at its promoter." (PMID 32218208, 2020).
neuroblastoma (5 papers, 2019 to 2025). Neuroblastoma (NB) is the most common solid, extracranial childhood tumor. "To elucidate the prognostic implications of MTHFD2 and PAICS in neuroblastoma progression, we analyzed the association of MTHFD2 and PAICS expressions with patient survival." (PMID 31624245, 2019). "One study has reported that PAICS can promote tumor proliferation and migration in neuroblastoma, though it has also been shown to play an important role in a variety of tumors." (PMID 35361282, 2022). "Poor overall and event-free survivals were found in highly expressed MTHFD2 or PAICS neuroblastoma patients." (PMID 31624245, 2019). "Altogether, the patient survival yielded consistent results as the drug combination assays that simultaneously suppressing MTHFD2 and PAICS expressions showed a synergism in MNA neuroblastoma patients." (PMID 31624245, 2019). "As in the single knockdown results, shMTHFD2 cells decreased by 49.3%, while that of shPAICS cells decreased by 38.4% compared to shLacZ control, suggesting silencing of MTHFD2 and PAICS had synergistic effect on migration ability in MNA neuroblastoma." (PMID 31624245, 2019). "Next, we examined the MTHFD2/PAICS gene combinations with synergistic effects on neuroblastoma patient survival." (PMID 31624245, 2019). "Our dual knockdown and co-treatment assays that target MTHFD2 and PAICS had synergistic effects on MNA neuroblastoma which might diminish the aggressiveness and tumor progression ability." (PMID 31624245, 2019). "The results suggest that the synergistic effect of MTHFD2 and PAICS are related to the biosynthesis of nucleotides, as well as their interconnection in one carbon by folate and purine metabolism in MNA neuroblastoma cells." (PMID 31624245, 2019). "Dual knockdown of the MYCN-targeted gene pair, MTHFD2 and PAICS, in MNA neuroblastoma cells synergically reduced cell proliferation, colony formation, migration ability, and DNA synthesis." (PMID 31624245, 2019). "To explore the impact of the two metabolic enzymes on MNA neuroblastoma, we first constructed stable knockdown of LacZ (control), MTHFD2, PAICS, and MTHFD2/PAICS (dual-knockdown) by delivering shRNA hairpins into MNA SK-N-DZ cells followed by puromycin selection." (PMID 31624245, 2019). "According to the impact of MTHFD2 and PACIS on neuroblastoma patient survival, we ascertain their stimulatory effects on cell proliferation by cell viability and colony formation assays in response to MTHFD2 and PAICS expression manipulation." (PMID 31624245, 2019). "Integrating anti-MYCN ChIP-seq and gene expression profiles of neuroblastoma patients revealed the metabolic enzymes, MTHFD2 and PAICS, required for one-carbon metabolism and purine biosynthesis were concomitantly upregulated, which were more susceptible to metastatic neuroblastoma." (PMID 31624245, 2019). "By systematically screening the compound perturbagens, the gene expression levels of MTHFD2 and PAICS were specifically suppressed by anisomycin and apicidin across cell lines, and our co-treatment results also displayed synergistic inhibition of MNA neuroblastoma cell proliferation." (PMID 31624245, 2019). "Next, we assessed the protein expression levels in six neuroblastoma cell lines, where the MNA cell lines had markedly higher endogenous expressions of MTHFD2 and PAICS compared to non-MNA cell lines." (PMID 31624245, 2019). "We first evaluated the mRNA expression levels of MTHFD2, PAICS, and MYCN in 21 tissue samples from neuroblastoma patients (MNA: n = 9; non-MNA: n = 12)." (PMID 31624245, 2019).
glioblastoma (4 papers, 2020 to 2024). The most malignant astrocytic tumor (WHO grade IV). "The frequency of PAICS genetic alteration (∼4%) is high in Glioblastoma multiforme, Diffuse glioma and Lung squamous cell carcinoma, with “amplification” as the primary type of alteration." (PMID 38463398, 2024). "Results displayed that the protein expression of PAICS in glioblastoma tissues was higher than that in paired normal tissues (P < .05)." (PMID 34173716, 2021). "We further detected the mRNA expression levels of PAICS in 10 pairs of glioblastoma tissues and normal brain tissues." (PMID 34173716, 2021). "Western blotting was used to detect the protein level of PAICS in three paired glioblastoma tissues." (PMID 34173716, 2021). "Compared with the normal tissues, the expression level of PAICS was up‐regulated in glioblastoma tissues." (PMID 34173716, 2021). "To confirm the results of bioinformatics analysis, we detected PAICS expression in glioblastoma and normal tissue samples by RT‐qPCR and Western blotting." (PMID 34173716, 2021). "To determine if tumor recurrence in glioblastoma patients who have undergone TMZ chemotherapy is associated with an increase in de novo purine synthesis enzyme expression, we performed IHC to determine the expression of metabolic enzymes DHFR, MTHFD2, and PAICS in ID-1-high patients." (PMID 39455562, 2024).
glioma (4 papers, 2013 to 2024). A benign or malignant brain and spinal cord tumor that arises from glial cells (astrocytes, oligodendrocytes, ependymal cells). "PAICS may act as a potential diagnostic marker and a therapeutic target for glioma." (PMID 34173716, 2021). "Double luciferase activity and chromatin immunoprecipitation assay results indicated that SPI1 can bind to the promoter sites and promote the proliferation and migration of glioma cells by regulating the expression of oncogenic PAICS." (PMID 35361282, 2022). "In order to understand SPI1 functionality in glioma progression, we knocked down PAICS expression with siRNAs in the U87 and U251 cells, respectively." (PMID 35361282, 2022). "Our goal was to explore the role of SPI1 in the occurrence and development of glioma with regards to regulation of PAICS, and provide a new direction for further exploration of glioma pathogenesis." (PMID 35361282, 2022). "To date, no studies have reported on the relationship between SPI1 Phosphoribosylaminoimidazole Carboxylase and Phosphoribosylaminoimidazolesuccinocarboxamide Synthase (PAICS) in glioma." (PMID 35361282, 2022). "The results demonstrated that PAICS was able to reverse the decrease in proliferation and migration of glioma cells induced by SPI1 interference." (PMID 35361282, 2022). "In this study, we elucidated that the hub genes phosphoribosylaminoimidazolesuccinocarboxamide synthase (PAICS) is over‐expressed in glioma tissues." (PMID 34173716, 2021). "Our results provide novel insights into the function of PAICS as a biomarker and a therapeutic target in glioma." (PMID 34173716, 2021). "PAICS expression level was significantly up‐regulated in glioma tissues compared with that in adjacent normal tissues, based on Oncomine microarray data set and web data‐mining online platform results." (PMID 34173716, 2021). "We observed that PAICS protein expression was increased in I‐II grade glioma tissues compared with in the normal tissues (P < .05) and significantly higher in grade III‐IV tissues than in normal tissues (P < .001)." (PMID 34173716, 2021). "To understand PAICS functionality in glioma progression, we knocked down the PAICS expression with siRNA‐309 and siRNA‐424 in U87 and U251 cells, respectively, and screened out the siRNA‐424 with the highest efficiency." (PMID 34173716, 2021). "A data set of a large number of glioma samples from the Oncomine database showed that the expression of PAICS in glioma tissues was obviously up‐regulated compared with that in normal tissues." (PMID 34173716, 2021). "Flow cytometry revealed that decrease the expression of PAICS in U87 and U251 cells promoted the proportion of cells in G0/G1 phase, while inhibited the proportion of glioma cells in S phase." (PMID 34173716, 2021). "Our previous study also found that PAICS plays an oncogene role in glioma." (PMID 35361282, 2022). "The role of SPI1 in the development of glioma is related to regulation of PAICS." (PMID 35361282, 2022). "Expression level of PAICS in different grades of glioma was examined by immunohistochemistry." (PMID 34173716, 2021). "l‐aspartic acid can affect the expression of PAICS and then inhibit glioma cell proliferation." (PMID 34173716, 2021). "Furthermore, we observed that PAICS expression level was up‐regulated in glioma tissues compared with normal tissues, and the expression level was correlated with the grade of glioma." (PMID 34173716, 2021). "Furthermore, we found that decrease the expression of PAICS increasing apoptotic rate of glioma cells." (PMID 34173716, 2021). "In addition, we found that l‐aspartic acid can affect the expression of PAICS and thus inhibit the proliferation of glioma cells." (PMID 34173716, 2021). "Then, we detected the expression of PAICS in gliomas of different grades and found that the expression of PAICS in gliomas of grade III and IV was significantly increased compared with normal brain tissue and gliomas of grades I‐II." (PMID 34173716, 2021).